NDUFB7 (NADH:ubiquinone oxidoreductase subunit B7)
Description:
Accessory subunit of the mitochondrial membrane respiratory chain NADH dehydrogenase (Complex I), that is believed not to be involved in catalysis. Complex I functions in the transfer of electrons from NADH to the respiratory chain. The immediate electron acceptor for the enzyme is believed to be ubiquinone.
Synonyms: CI-B18; B18; MGC2480; MC1DN39
Tractability: Small molecule: an approved drug acts on it; a structure with a bound ligand is known. Antibody: UniProt places it where antibodies can reach, with high confidence. PROTAC: ubiquitination databases record sites on it; its protein half-life has been measured.
Target class: Enzyme; Oxidoreductase
Gene: Protein-coding gene on chromosome 19 (14,566,078 to 14,572,066, reverse strand). Ensembl gene ENSG00000099795.
Subcellular location: Mitochondrion inner membrane; Mitochondrion intermembrane space
Pathways (Reactome):
Metabolism: Complex I biogenesis; Respiratory electron transport
Gene Ontology:
Molecular function: NADH dehydrogenase (ubiquinone) activity; protein binding
Biological process: aerobic respiration; mitochondrial electron transport, NADH to ubiquinone; proton motive force-driven mitochondrial ATP synthesis; proton transmembrane transport
Cellular component: mitochondrial inner membrane; mitochondrial intermembrane space; mitochondrion; respiratory chain complex I
Genetic constraint (gnomAD): Loss-of-function variants: 18 observed, 11.13 expected, observed/expected ratio (o/e) 1.62, 90% interval 1.08 to 1.95. The upper end of that interval is the gene's LOEUF score, 1.95, which puts it in group 6 of 6, group 1 being the genes least tolerant of losing a copy. Missense variants: 219 observed, 173.79 expected, observed/expected ratio (o/e) 1.26, 90% interval 1.13 to 1.41. Synonymous variants: 86 observed, 65.74 expected, observed/expected ratio (o/e) 1.31, 90% interval 1.1 to 1.57.
Gene-disease validity (ClinGen):
ClinGen rates the evidence that NDUFB7 causes each of these diseases.
mitochondrial disease (autosomal recessive): Limited.
Homologues: Orthologues: chimpanzee NDUFB7 (99% identical), macaque NDUFB7 (91% identical), pig NDUFB7 (85% identical), mouse Ndufb7 (82% identical), dog NDUFB7 (80% identical), rat Ndufb7 (80% identical), guinea pig NDUFB7 (77% identical), zebrafish ndufb7 (53% identical), tropical clawed frog ndufb7 (51% identical), Caenorhabditis elegans ndub-7 (44% identical), Drosophila melanogaster ND-B18 (44% identical).
Diseases named in the same sentence as NDUFB7 in open-access papers:
NDUFB7 is named in the same sentence as 21 diseases in open-access papers, as found by Europe PMC text mining. Sharing a sentence is not in itself a finding about the gene and the disease. The quoted sentences say what the papers report.
cardiomyopathy (3 papers, 2019 to 2025). A disease of the heart muscle or myocardium proper. "Of transcripts associated with cardiomyopathy, hypertrophy, and left ventricle alterations, Q‐PCR analysis was used to monitor the modulation of Ndufb7, Tnnt2, Ttn, Tnni3, and Plag2a." (PMID 37960940, 2023). "Interestingly, changes in FGF21-responsive genes such as OXCT1, the SUCL complex, PDHA1, OGDH, ACO2, IDH3B, and ETC components (MT-CO2, COQ9, UQCRQ, SDHB/D and NDUFB7) are linked to mitochondrial deficiency syndromes manifesting cardiomyopathy and encephalopathy." (PMID 40998786, 2025).
lactic acidosis (3 papers, 2019 to 2025). Metabolic acidosis characterized by the accumulation of lactate in the body. "In this case, an intronic mutation in NDUFB7 caused severe congenital lactic acidosis and hypertrophic cardiomyopathy." (PMID 38151566, 2023).
Parkinson’s (2 papers, 2016 to 2018). "The two subunits of mitochondrial complex I NDUFB7 and NDUFA13 are associated with Alzheimer’s, Parkinson’s and Huntington’s diseases." (PMID 27314336, 2016). "Next we interrogated the KEGG pathway and found the top up-regulated categories showed strong correlation with Alzheimer’s, Huntington’s and Parkinson’s diseases by enriching genes such as ATP5D, ATP5H, HSD17B10 and NDUFB11, NDUFA8, NDUFB7, NDUFS8." (PMID 29915338, 2018).
breast carcinoma (1 paper, 2020). "Genes such as NDUFB1, NDUFB2, and NDUFB7 were found to have significant prognostic values for breast cancer patients." (PMID 32785169, 2020).
psoriatic arthritis (1 paper, 2025). Joint inflammation associated with psoriasis. "A small study recognized NDUFB7, a complex I subunit, as a promising biomarker of psoriatic arthritis." (PMID 40565008, 2025).
tumor (2 papers, 2020 to 2022). "Further, the expression of NDUFB7, AURKAIP1, ROMO1, SCAND1, GADD45GIP1, and NDUFA13 was upregulated in the four tumor subtypes compared with normal adjacent tissue." (PMID 34996995, 2022). "However, the correlation between UQCRQ, NDUFB7 and UQCRC2 in modulating mitochondrial energy generation and tumour progression remains unclear and needs to be confirmed by further experiments." (PMID 32757436, 2020).
cancer (1 paper, 2025). A tumor composed of atypical neoplastic, often pleomorphic cells that invade other tissues. "In fast-running racehorse breeds, the SNP with the highest Fst ranking was found to involve NDUFB7, and this gene is directly regulated by PPARA in cancer models." (PMID 40723531, 2025).
mitochondrial disease (1 paper, 2025). "All evidence supports the pathological role of NDUFB7 in mitochondrial diseases." (PMID 40025060, 2025).
neurodegenerative disease (1 paper, 2024). A disorder of the central nervous system characterized by gradual and progressive loss of neural tissue and neurologic function. "GO and KEGG analyses of ME7 also identified upregulation of genes related to mitochondrial oxidative phosphorylation, including NDUFS6, NDUFA13, NDUFB7, NDUFA3, and NDUFS5, which are involved in a variety of neurodegenerative diseases." (PMID 37971544, 2024).
NDUFB7 also shares sentences with these, for which no sentence is quoted: hypertrophic cardiomyopathy (2 papers); AIDS (1); Alzheimer disease (1); anemia (1); Encephalopathy (1); gastric cancer (1); growth deficiency (1); Huntington disease (1); hypertrophy (1); infection (1); macrosomia (1); ventral hernia (1).